PIK3R3 (phosphoinositide-3-kinase regulatory subunit 3)
Description:
Binds to activated (phosphorylated) protein-tyrosine kinases through its SH2 domain and regulates their kinase activity. During insulin stimulation, it also binds to IRS-1.
Synonyms: p55; p55-GAMMA; p55PIK
Tractability: Small molecule: a drug acting on it is in phase 2 or 3 trials; a high-quality ligand is known. PROTAC: ubiquitination databases record sites on it; a small molecule that binds it is known.
Target class: Kinase; Protein kinase regulatory subunit; Enzyme
Gene: Protein-coding gene on chromosome 1 (46,040,140 to 46,133,338, reverse strand). Ensembl gene ENSG00000117461.
Subcellular location (Human Protein Atlas): Cytosol; Nucleoplasm; Connecting piece; End piece; Mid piece; Principal piece
Pathways (Reactome):
Signal Transduction: Extra-nuclear estrogen signaling; G alpha (q) signalling events; PI5P, PP2A and IER3 Regulate PI3K/AKT Signaling; PIP3 activates AKT signaling; RAC1 GTPase cycle; RAC2 GTPase cycle; Signaling by SCF-KIT
Immune System: CD28 dependent PI3K/Akt signaling; Co-stimulation by ICOS; Interleukin receptor SHC signaling; Interleukin-3, Interleukin-5 and GM-CSF signaling; Interleukin-7 signaling; Regulation of signaling by CBL
Disease: Constitutive Signaling by Aberrant PI3K in Cancer; Signaling by phosphorylated juxtamembrane, extracellular and kinase domain KIT mutants
Developmental Biology: RET signaling
Hemostasis: GPVI-mediated activation cascade
Metabolism: Synthesis of PIPs at the plasma membrane
Gene Ontology:
Molecular function: phosphotyrosine residue binding; protein binding; 1-phosphatidylinositol-3-kinase activity; 1-phosphatidylinositol-3-kinase regulator activity
Biological process: cell migration involved in sprouting angiogenesis; phosphatidylinositol 3-kinase/protein kinase B signal transduction; positive regulation of gene expression; B cell differentiation; immune response; insulin receptor signaling pathway; negative regulation of anoikis; positive regulation of cell migration; T cell differentiation; phosphatidylinositol-3-phosphate biosynthetic process
Cellular component: cytosol; phosphatidylinositol 3-kinase complex, class IA; phosphatidylinositol 3-kinase complex
Genetic constraint (gnomAD): Loss-of-function variants: 24 observed, 21.96 expected, observed/expected ratio (o/e) 1.09, 90% interval 0.79 to 1.53. The upper end of that interval is the gene's LOEUF score, 1.53, which puts it in group 6 of 6, group 1 being the genes least tolerant of losing a copy. Missense variants: 285 observed, 247.56 expected, observed/expected ratio (o/e) 1.15, 90% interval 1.04 to 1.27. Synonymous variants: 67 observed, 85.81 expected, observed/expected ratio (o/e) 0.78, 90% interval 0.64 to 0.96.
Homologues: Orthologues: chimpanzee PIK3R3 (99% identical), rabbit PIK3R3 (99% identical), dog PIK3R3 (99% identical), pig PIK3R3 (98% identical), guinea pig PIK3R3 (97% identical), mouse Pik3r3 (96% identical), macaque PIK3R3 (93% identical), rat Pik3r3 (89% identical), tropical clawed frog pik3r3 (89% identical), zebrafish pik3r3b (87% identical), zebrafish pik3r3a (37% identical), Drosophila melanogaster Pi3K21B (33% identical), and 1 more. Paralogues in human: PIK3R1 (75% identical), PIK3R2 (67% identical).
Diseases named in the same sentence as PIK3R3 in open-access papers:
PIK3R3 is named in the same sentence as 83 diseases in open-access papers, as found by Europe PMC text mining. Sharing a sentence is not in itself a finding about the gene and the disease. The quoted sentences say what the papers report.
colorectal cancer (26 papers, 2011 to 2025). A primary or metastatic malignant neoplasm that affects the colon or rectum. "In a study conducted on colorectal cancer cells, curcumin reduced the aggressiveness of cells by acting via the circHN1/miR-302a-3p/PIK3R3 pathway." (PMID 41010991, 2025). "displayed that PIK3R3 promoted colorectal cancer metastasis via SNAI2‐induced epithelial‐to‐mesenchymal transition, suggesting a potential target for metastatic colorectal cancer." (PMID 39692250, 2024). "In colorectal cancer, miR-193a functioned through the miR-193a-5p/PIK3R3/AKT axis, playing a role in the initiation and progression of the disease." (PMID 38216907, 2024). "A previous study revealed that PIK3R3 promotes chemotherapeutic sensitivity of colorectal cancer via the NF-κB/TP pathway." (PMID 37644421, 2023). "In colorectal cancer, for example, circRNA_0000392 can promote tumor progression via the miR‐193a‐5p/PIK3R3/AKT axis." (PMID 36268976, 2022). "PIK3R3 had been reported to be upregulated in diverse tumors, such as ovarian cancer, colorectal cancer, and glioma." (PMID 33407443, 2021). "PIK3R3 is a known oncogene, which accelerated a range of tumors development, such as cervical cancer, ovarian cancer, glioma, and colorectal cancer." (PMID 33407443, 2021). "PIK3R3 has recently emerged as a tumor promoter in a number of malignancies, including glioblastoma, ovarian and colorectal carcinoma, and leukemia." (PMID 25603314, 2015). "Furthermore, the downregulation of PIK3R3 reversed this process, potentially leading to increased invasion and metastasis of colorectal cancer cells." (PMID 38420127, 2024). "However, PIK3R3 overexpression promotes chemotherapeutic sensitivity and apoptosis in colorectal cancer cells." (PMID 34366863, 2021). "However, higher expression of PIK3R3 has been reported in cancer patients with satisfactory colorectal cancer outcomes as it facilitated the apoptosis of cancer cells." (PMID 33329703, 2020). "The gene PIK3R3 has been reported to play an important role in colorectal cancer metastasis." (PMID 31514484, 2019). "Blocking PIK3R3 can prevent colorectal cancer liver metastasis in animal model." (PMID 31514484, 2019). "PIK3R3 was identified as a target gene of miR-193a-5p in colorectal cancer cells, mediating the effects of miR-193a-5p and circRNA_0000392, and enhancing AKT signaling, the miR-193a-5p inhibitor can alleviate the reduction in PIK3R3 expression caused by circRNA_0000392 siRNA." (PMID 40161373, 2025). "More importantly, we explored the mechanism of circRNA_0000392 in the progression of colorectal cancer and found that it could act as a sponge of miR-193a-5p, thereby releasing the inhibition of PIK3R3 by miR-193a-5p and promoting the phosphorylation of the AKT/mTOR signaling pathway." (PMID 33317596, 2020). "Downregulating circRNA_0000392 decreases the levels of PIK3R3 protein and the phosphorylation levels of AKT and mTOR, thereby reducing the growth of colorectal cancer cells in vivo." (PMID 40161373, 2025). "Consistent with previous studies, the overexpression of PIK3R3 has been reported to benefit cell proliferation of HCC, colorectal cancer, and oral squamous cell carcinoma, and vice versa." (PMID 37212524, 2023). "For example, PIK3R3 expression has been upregulated in HCC, colorectal cancer, cervical cancer, and non‐small cell lung cancer." (PMID 37212524, 2023).
colorectal cancer (continued). "CircRNA_0000392 functions as an oncogene through the miR-193a-5p/PIK3R3/Akt axis in CRC cells, suggesting that circRNA_0000392 is a potential therapeutic target for the treatment of colorectal cancer and a predictive marker for CRC patients." (PMID 33317596, 2020). "PIK3R3, an isoform of class IA phosphoinositide 3-kinase (PI3K), that specifically interacts with cell proliferation regulators and promotes metastasis and EMT in colorectal cancer, was also up-regulated in SSA/Ps." (PMID 29284484, 2017).
ovarian carcinoma (16 papers, 2012 to 2023). A malignant neoplasm originating from the surface ovarian epithelium. "We aimed to determine the potential of PIK3R3 as a predictive marker of ovarian cancer and to regulate PIK3R3 expression in somatically mutated ovarian cancer cells." (PMID 35761259, 2022). "Using muTAR analysis, PIK3R3 was highly expressed in several somatically mutated ovarian cancers and was predictive of ovarian cancer response to Avastin® chemotherapy." (PMID 35761259, 2022). "To understand the role of PIK3R3 in the molecular mechanisms underlying ovarian cancer development, we used bioinformatics approaches." (PMID 35761259, 2022). "muTarget was used to identify mutations that alter PIK3R3 expression in ovarian cancer." (PMID 35761259, 2022). "In addition, it has been reported that mutation of PIK3R3 is related to ovarian cancer and PIK3R3 is a potential therapeutic target for ovarian cancer." (PMID 28615526, 2017). "PIK3R3 expressions have been associated with cancers like glioblastoma and ovarian cancer in prior studies, and recent studies have identified PIK3R3/AKT as the target of lung cancer molecule miR-7 which affects TLR9 signaling (TLR was discussed in a previous section)." (PMID 24369052, 2013). "Thus, our data imply that PIK3R3 is associated with stem-like properties of ovarian cancer cells." (PMID 35761259, 2022). "Available data have also shown aberrant expression of PIK3R3 in ovarian cancer and sarcoma, indicating a promoting role of PIK3R3 in oncogenesis." (PMID 37644421, 2023). "Elevated PIK3R3 levels were observed in ovarian cancer stem cells, wherein inhibiting PIK3R3 expression significantly reduced the size of ovarian cancer spheroids." (PMID 35761259, 2022). "A previous study showed that the level of PIK3R3 is significantly expressed in ovarian cancer cell lines including HGSOC cell lines (PEO1, OVCAR3, OVCAR4, OVCAR8, OVCAR10) than in human ovarian surface epithelial cells." (PMID 35761259, 2022). "In this study, PIK3R3 was highly expressed in serous ovarian carcinoma and ovarian clear cancer compared to normal ovary using public datasets and was upregulated in ovarian cancer stem cells (A2780-SP and SKOV3-SP)." (PMID 35761259, 2022). "PIK3R3 plays a pivotal role in ovarian cancer development and is therefore a potential candidate for developing novel therapeutic approaches." (PMID 35761259, 2022). "We also aimed to deduce the role of PIK3R3 in the maintenance of stem cell properties in ovarian cancer cells." (PMID 35761259, 2022). "PIK3R3 is overexpressed in ovarian cancer cells; however, its exact function is not well understood." (PMID 35761259, 2022). "PIK3R3 expression in ovarian cancer positively correlated with sex determining region Y-box 2 (SOX2), CD44, and aldehyde dehydrogenase 1 (ALDH1A1)." (PMID 35761259, 2022). "In this study, we identified PIK3R3 as a potential biomarker for determining the effectiveness of Avastin® treatment and predicting progression-free survival in ovarian cancer patients." (PMID 35761259, 2022). "ROC plotter analysis was conducted to understand the potential of PIK3R3 as a predictive marker for effectiveness of therapy in ovarian cancer." (PMID 35761259, 2022). "miR-186 modulated the ovarian cancer cells' cisplatin sensitivity by downregulating PIK3R3 and PTEN while enhancing the regulation of APAF1." (PMID 34804161, 2021). "The expression of both HOTAIR and PIK3R3 was downregulated when ovarian cancer cells were transfected with miR-214 or miR-217 mimics." (PMID 34204094, 2021). "It was demonstrated that PTEN and PIK3R3 were two functional targets of miR-186 in lung adenocarcinoma 21 and in ovarian cancer." (PMID 32284740, 2020). "Thus, our results suggest that PIK3R3 is a potential prognostic biomarker for Avastin®-mediated treatment of ovarian cancer." (PMID 35761259, 2022). "PIK3R3 expression is upregulated in ovarian cancer as well as ovarian CSCs." (PMID 35761259, 2022).
ovarian carcinoma (continued). "Our study shows that PIK3R3 is an important regulator of both ovarian cancer and ovarian CSCs." (PMID 35761259, 2022). "PIK3R3 is a relatively sensitive marker for predicting the effect of Avastin® treatment on patients with ovarian cancer based on relapse-free survival at 6 months (area under the curve [AUC] = 0.809, P = 2.2E-02) and pathological response (AUC = 0.664, P = 3.1E-02)." (PMID 35761259, 2022). "Together, our findings support the position that PIK3R3 may be a crucial regulator of ovarian cancer development." (PMID 35761259, 2022). "ROC plotter analysis of drug responses showed that PIK3R3 may be a potential predictive biomarker for Avastin®-mediated ovarian cancer treatment." (PMID 35761259, 2022). "It needs to further study the relationship between PIK3R3 and ErbB signaling in ovary cancer." (PMID 35761259, 2022). "We concluded that PTEN and PIK3R3 were two targets in cisplatin-resistant ovarian cancer cells." (PMID 32284740, 2020). "Thus, our study suggests that PIK3R3 affects ovarian cancer via the ErbB signaling pathway." (PMID 35761259, 2022). "Furthermore, HOTAIR promotes proliferation of ovarian cancer cells through regulating PIK3R3." (PMID 27367027, 2016). "Interestingly, PIK3R3 has increased expression in glioblastoma multiforme and ovarian cancer." (PMID 22876838, 2012). "The HOXD-AS1/miR-186-5p/PIK3R3 pathway has been found to play an important role in invasion, migration and EMT of epithelial ovarian cancer." (PMID 37993951, 2023). "PIK3R3 expression was lower in USP4, SPTBN1, and SORBS2-mutant ovarian cancer patients than in ovarian cancer patients with wild type genes." (PMID 35761259, 2022). "Studies have shown that PIK3R3 expression levels in CRC and ovarian cancer tissues exhibit the same trend, which is consistent with our results." (PMID 33317596, 2020). "We verified PIK3R3 and PTEN were the two targets of miR-186, and overexpression of miR-186 decreased the protein levels of PIK3R3 and PTEN in cisplatin-resistant ovarian cancer cells." (PMID 32284740, 2020). "Knockdown of PIK3R3 inhibits IGF2-induced cell growth in glioblastoma multiforme and induces apoptosis in ovarian cancer cells." (PMID 22876838, 2012). "We compared PIK3R3 expression to Avastin® treatment in ovarian cancer specimens responders and non-responders." (PMID 35761259, 2022). "PIK3R3, the gene that encodes the PI3K regulatory subunit p55γ, is over-expressed in glioblastoma and ovarian cancers, but its expression in gastric cancer (GC) is not known." (PMID 22876838, 2012). "Cystadenocarcinoma, serous, and endometrioid carcinoma tissues were stained “medium” or “weak” for PIK3R3, whereas no detectable intensity was observed for normal tissues (described as “not detected”), suggesting that PIK3R3 expression is specifically upregulated in ovarian carcinomas." (PMID 35761259, 2022).
breast carcinoma (12 papers, 2012 to 2022). "As such over expression of PIK3R3 has been associated with ovarian, liver, prostate and breast cancers." (PMID 22737227, 2012). "Eight of these genes (except WNT2, GADD45B, FZD2, WNT7B, POLK, and PIK3R3) have been extensively studied in breast cancer." (PMID 32818022, 2020). "For instance, genome-wide association studies performed by the Breast Cancer Association Consortium showed that BRCA2, CHEK2, ESR1, FGFR2, MDM4 and PIK3R3 carry germline variants associated with BC development." (PMID 32210335, 2020). "Therefore, we further analyzed the correlation between RBP7 and PIK3R3 in breast cancer and found that the expression levels of RBP7 and PIK3R3 were negatively correlated (R = −0.231, p = 6.79e − 15)." (PMID 36276273, 2022). "Interestingly, in this interacting network, PIK3R3, a regulatory subunit of phosphatidylinositol 3-kinase (PI3K), was reported to play an important role in breast cancer." (PMID 36276273, 2022). "In addition, AKT3 was targeted by miR-29 in breast cancer, and cytokine receptor (IL2RB and IL6R) and one component of the PI3K complex (PIK3R3) were also targeted by miR-34a and miR-29, respectively, in DLBCL." (PMID 30820547, 2019). "Also, 7 genes (CTGF, ESR1, MAPK3, PIK3R3, PLAU, PRNP, and RET) were reported to be highly relevant to growth (P<1E-04) and microtubule dynamics (P<4E-05) in tumor cell lines, and apoptosis in breast cancers (P<1E-04)." (PMID 23185353, 2012).
hepatocellular carcinoma (11 papers, 2020 to 2024). A malignant tumor that arises from hepatocytes. "It has been reported that the LINC00160 knock down reduced the levels of PIK3R3 through miR-132 up regulation that resulted in reduced hepatocellular carcinoma (HCC) tumor cell drug resistance." (PMID 34419060, 2021). "PIK3R3 has been elucidated to be highly expressed in drug-resistant hepatocellular cancer cells, which is in accordance with our findings." (PMID 34853725, 2021). "In hepatocellular carcinoma, miR-513b-5p inhibits PIK3R3 expression and represses autophagy." (PMID 34858987, 2021).
lung cancer (11 papers, 2013 to 2025). A malignant neoplasm involving the lung. "explored the mechanisms of miR-193a-5p in regulating lung cancer metastasis by downregulating the ERBB4/PIK3R3/mTOR/S6K2 signaling pathway." (PMID 40230863, 2025). "Studies have found that TLR9 can promote the progression of lung cancer, and miR-7 can inhibit the growth and metastasis of lung cancer cells by regulating the PIK3R3/Akt pathway and inhibiting the TLR9 signaling pathway." (PMID 37627250, 2023). "After multiple-testing correction, 112 SNPs in eight genes (ATR, EGFR, MET, PIK3R1, PIK3R3, PTPN2, STAT3, and STAT5A) remained significantly associated with lung cancer risk with FDR <0.20." (PMID 28400551, 2017). "MicroRNA-193a-3p and −5p function as tumour suppressors and inhibit the metastasis of lung cancer by down-regulating the ERBB4/PIK3R3/mTOR/S6K2 signalling pathway." (PMID 26395400, 2015). "In previous study, we reported down-regulation of intrinsic miR-7 was critical for TLR9 signaling enhanced progression of human lung cancer cells through altering the expression of PIK3R3." (PMID 24004462, 2013). "Focusing on miRNA and TLR signalling in cancer, it was recently demonstrated that TLR9 stimulation increases the growth and metastatic features of lung cancer cells via the downregulation of miR-7 and the resulting regulation of phosphoinositide-3-kinase regulatory subunit 3 (PIK3R3)/Akt pathway." (PMID 23551576, 2013). "miR-7 is also shown to target phosphoinositide-3-kinase regulatory subunit 3 (PIK3R3) in lung cancer cells, and the down-regulation of the PIK3R3/Akt pathway attenuates the TLR9 signaling-induced growth and proliferation of lung cancer cells." (PMID 36555120, 2022).